BRAF (B-Raf proto-oncogene, serine/threonine kinase)
Description:
Protein kinase involved in the transduction of mitogenic signals from the cell membrane to the nucleus (Probable). Phosphorylates MAP2K1, and thereby activates the MAP kinase signal transduction pathway. Phosphorylates PFKFB2. May play a role in the postsynaptic responses of hippocampal neurons.
Synonyms: BRAF1; RAFB1; BRAF-1; B-RAF1; B-raf; NS7
Tractability: Small molecule: an approved drug acts on it; a structure with a bound ligand is known; a high-quality ligand is known; it has a high-quality binding pocket; it belongs to a druggable protein family. Antibody: UniProt places it where antibodies can reach, with high confidence; its Gene Ontology location is reachable by antibodies, with high confidence; the Human Protein Atlas places it where antibodies can reach. PROTAC: it is named in the literature on targeted protein degradation; UniProt records ubiquitination sites on it; ubiquitination databases record sites on it; its protein half-life has been measured; a small molecule that binds it is known.
Target class: Kinase; Enzyme; TKL protein kinase RAF family; Protein Kinase; TKL protein kinase group
Chemical probes: GDC-0879 (high quality), P4B (high quality), PD080847, PD083763, PD083988, PD084167, PD084517, PD085072, PD134482, PD134488, PD134489, PD134490, PD134492, PD134493, PD134494, PD134495, PD144366, PD144367, PD144368, RAF709
Safety:
Unwanted effects reported when the protein is acted on. In parentheses: how it was acted on, where the effect was seen, and who reports it.
heart disease (cardiovascular system; source: Force et al. (2011))
Gene: Protein-coding gene on chromosome 7 (140,719,327 to 140,924,976, reverse strand). Ensembl gene ENSG00000157764.
Subcellular location: Nucleus; Cytoplasm; Cell membrane
Subcellular location (Human Protein Atlas): Cytosol; Vesicles; Basal body; Centriolar satellite; End piece; Mid piece; Plasma membrane; Primary cilium; Principal piece
Pathways (Reactome):
Disease: Gain-of-function MRAS complexes activate RAF signaling; Paradoxical activation of RAF signaling by kinase inactive BRAF; SHOC2 M1731 mutant abolishes MRAS complex function; Signaling by BRAF and RAF1 fusions; Signaling by RAF1 mutants; Signaling by high-kinase activity BRAF mutants; Signaling by moderate kinase activity BRAF mutants; Signaling downstream of RAS mutants
Signal Transduction: ARMS-mediated activation; Frs2-mediated activation; MAP2K and MAPK activation; Negative feedback regulation of MAPK pathway; Negative regulation of MAPK pathway; RAF activation; Signalling to p38 via RIT and RIN; Spry regulation of FGF signaling
Gene Ontology:
Molecular function: calcium ion binding; identical protein binding; MAP kinase kinase activity; protein binding; protein kinase activity; protein serine kinase activity; protein serine/threonine kinase activity; scaffold protein binding; small GTPase binding; MAP kinase kinase kinase activity; ATP binding
Biological process: cellular response to calcium ion; epidermal growth factor receptor signaling pathway; establishment of protein localization to membrane; MAPK cascade; negative regulation of apoptotic process; positive regulation of D-glucose transmembrane transport; positive regulation of ERK1 and ERK2 cascade; positive regulation of gene expression; positive regulation of peptidyl-serine phosphorylation; animal organ morphogenesis; protein phosphorylation; postsynaptic modulation of chemical synaptic transmission; signal transduction
Cellular component: cytoplasm; cytosol; plasma membrane; mitochondrion; cell body; glutamatergic synapse; neuron projection; nucleus; postsynapse
Genetic constraint (gnomAD): Loss-of-function variants: 14 observed, 92.18 expected, observed/expected ratio (o/e) 0.15, 90% interval 0.099 to 0.24. The upper end of that interval is the gene's LOEUF score, 0.24, which puts it in group 1 of 6, group 1 being the genes least tolerant of losing a copy. Missense variants: 477 observed, 874.65 expected, observed/expected ratio (o/e) 0.55, 90% interval 0.5 to 0.59. Synonymous variants: 281 observed, 321.07 expected, observed/expected ratio (o/e) 0.88, 90% interval 0.79 to 0.97.
Gene-disease validity (ClinGen):
ClinGen rates the evidence that BRAF causes each of these diseases.
cardiofaciocutaneous syndrome (autosomal dominant): Definitive. Cardiofaciocutaneous (CFC) syndrome is a RASopathy characterized by craniofacial dysmorphology, congenital heart disease, dermatological abnormalities (most commonly hyperkeratotic skin and sparse, curly hair), growth retardation and intellectual disability.
Noonan syndrome (autosomal dominant): Moderate. Noonan Syndrome (NS) is characterized by short stature, typical facial dysmorphism and congenital heart defects.
Noonan syndrome with multiple lentigines (autosomal dominant): Limited. A rare multisystem genetic disorder characterized by lentigines, hypertrophic cardiomyopathy, short stature, pectus deformity, and dysmorphic facial features.
Costello syndrome (autosomal dominant): Disputed. Costello syndrome (CS) is a rare multisystemic disorder characterized by failure to thrive, short stature, developmental delay or intellectual disability, joint laxity, soft skin, and distinctive facial features.
Cancer hallmarks: proliferative signalling (promotes); escaping programmed cell death (promotes)
Homologues: Orthologues: chimpanzee BRAF (100% identical), chimpanzee BRAF (99% identical), macaque BRAF (98% identical), dog BRAF (98% identical), pig BRAF (98% identical), rat Braf (97% identical), rabbit BRAF (93% identical), mouse Braf (92% identical), guinea pig BRAF (87% identical), tropical clawed frog braf (86% identical), zebrafish braf (83% identical). Paralogues in human: RAF1 (49% identical), ARAF (46% identical), KSR1 (19% identical), KSR2 (19% identical), TNNI3K (18% identical), LRRK2 (17% identical), MAP3K9 (17% identical), MAP3K10 (16% identical), MAP3K11 (16% identical), MAP3K21 (16% identical), LIMK2 (15% identical), LIMK1 (15% identical), and 11 more.
Diseases named in the same sentence as BRAF in open-access papers:
BRAF is named in the same sentence as 885 diseases in open-access papers, as found by Europe PMC text mining. Sharing a sentence is not in itself a finding about the gene and the disease. The quoted sentences say what the papers report.
melanoma (6,782 papers, 2003 to 2026). A malignant, usually aggressive tumor composed of atypical, neoplastic melanocytes. "A pilot ddPCR study similarly found low-level RAS/BRAF variants detectable in normal skin of patients in whom nevi and melanomas shared the same MAPK driver." (PMID 41516405, 2026). "Apart from primary CNS tumors, genetic alterations within the MAPK pathway, such as RTK and BRAF mutations, are often observed in brain metastases originating from lung, breast, and melanoma primary cancers." (PMID 41514664, 2026). "Although multiple somatic mutations contribute towards melanoma development, but the BRAF mutation is the most prevalent." (PMID 41982244, 2026). "Nearly 50 % of all cutaneous melanoma patients harbor a BRAF mutation, more frequent in melanomas of the trunk than those of the head and neck." (PMID 41450449, 2026). "Among these, BRAF mutations, especially the V600E variant, are the most prevalent, accounting for approximately 90% of BRAF-mutant melanomas." (PMID 41596235, 2026). "NRAS mutation status is an independent predictor of shorter overall survival (OS) in metastatic melanoma compared with BRAF mutation or BRAF/NRAS wild‐type melanoma." (PMID 41492362, 2026). "Such spatially regulated epitranscriptomic rewiring upregulates pro-survival genes (e.g., ATF4, HIF1A) while silencing proliferation drivers (e.g., MYC, CCND1), a hallmark of BRAF/MEK inhibitor-persistent melanoma cells." (PMID 41362736, 2026). "BRAF–MEK inhibitor combinations are standard for BRAF‐mutant melanoma, whereas targeting NRAS mutations is more challenging, with MEK inhibitors like tunlametinib emerging as an option." (PMID 41492362, 2026). "In 2002, a genome‐wide screening discovered that 66% of melanoma had BRAF somatic missense mutations, which were more frequent than other types of solid tumors." (PMID 41492362, 2026). "Under the microscope, NRAS mutation melanoma displayed a higher rate of mitosis (count of >1⁄mm2) compared with BRAF mutations and wild‐type melanoma." (PMID 41492362, 2026). "We retrospectively assessed frequency, response to therapy and outcome of rare BRAF mutations compared to V600E/K in cases from 19 Italian Melanoma group (IMI) centers." (PMID 42003243, 2026). "In this study, 24 melanoma patients were enrolled, including nine patients with BRAF mutation and two patients with NRAS mutation." (PMID 41492362, 2026). "Phosphodiesterase Type 4 (PDE4) is a cAMP‐specific enzymes that essential for the conversion from BRAF to CRAF in NRAS mutation melanoma through inhibiting cAMP signaling." (PMID 41492362, 2026). "Consistently, in melanoma cell lines carrying BRAF or NRAS mutation, GLI2 expression was stronger than in wild-type cells." (PMID 41596411, 2026). "A 2020 meta-analysis of 52 studies reported a significantly lower overall survival (OS) (HR 1.23; 95 % CI) in BRAF-mutated compared to wild-type melanoma, like the melanoma of our patient." (PMID 41450449, 2026). "Meanwhile, reactive oxygen species (ROS) can reactive ERK1/2, which is located at the center of MAPK pathway, indicating that ROS plays a crucial role in the resistance of BRAF and MEK inhibitors in BRAF mutation melanoma." (PMID 41492362, 2026). "Melanoma exhibits a high proliferative capacity largely due to frequent driver mutations, such as BRAF and NRAS." (PMID 41596235, 2026). "We focus on the clinical data of ICIs and optimized combination methods of ICIs and MEK inhibitors in NRAS/BRAF mutation melanoma." (PMID 41492362, 2026). "Constitutive activation of the mitogen-activated protein kinase (MAPK) signaling cascade, largely driven by BRAF mutations, is recognized as a key initiator of melanoma development." (PMID 41596235, 2026). "The increased invasion and metastasis of melanoma cells are linked to mutations in BRAF, NRAS, and NF1 genes." (PMID 42193039, 2026).
melanoma (continued). "Both pembrolizumab and nivolumab have demonstrated efficacy in reducing the risk of local and distant recurrence in patients with high-risk stage II melanoma, whereas evidence supporting the use of BRAF-MEK inhibitors in this setting remains inconclusive." (PMID 42279384, 2026). "This study investigated the distribution, prognostic role, and functional impact of rare BRAF mutations in melanoma." (PMID 42003243, 2026). "In BRAF-mutated melanoma, CDK12 is constitutively activated through phosphorylation by ERK1/2, a key effector of the RAS/MAPK signaling cascade." (PMID 41491919, 2026). "On the other hand, BRAF mutation melanoma shows distinct morphological features such as increased upward migration, sharper boundaries with surrounding skin, and larger, rounder, and more pigmented tumor cells." (PMID 41492362, 2026). "explored the combining of HDAC inhibitors (entinostat) with BRAF/MEK inhibitors in melanoma cells harboring BRAF, NRAS, PTEN, or NF1 mutations." (PMID 41492362, 2026). "When melanoma cells are grouped according to their genotype (WT vs. BRAF/NRAS-mutated), treatment with sonidegib results in a significant dose-dependent enhancement in the percentage of cells in the S phase only in mutant cells." (PMID 41596411, 2026). "A recent Korean study has revealed the value of belvarafenib in BRAF or NRAS mutation melanoma patients." (PMID 41492362, 2026). "In 2014, the combination of dabrafenib and trametinib was the first combination approved for the treatment of advanced melanoma with BRAF mutation in the United States." (PMID 41492362, 2026). "Despite a wide range of therapeutic options, including targeted therapy (in cases of BRAF-mutated melanoma), immune checkpoint inhibitors, and radiotherapy, drug resistance remains a major clinical challenge." (PMID 41596411, 2026). "Non-V600E/K BRAF mutations have been reported in melanoma, but data on their clinical relevance are conflicting." (PMID 42003243, 2026). "For BRAF mutated melanoma cells, abnormal activation of RAF protein kinase causes MEK phosphorylation and activates downstream pathways, such as ERK1 and ERK2." (PMID 41492362, 2026). "In this study, we investigated the molecular mechanisms underlying ONC-induced cytotoxicity in BRAF-mutated melanoma cell lines that are either sensitive or resistant to the BRAF inhibitor dabrafenib." (PMID 41751773, 2026). "Given the lack of satisfying target therapies for NRAS mutation melanoma and the proven efficacy of immunotherapy for melanoma, immunotherapy is considered as another potential strategy for NRAS/BRAF mutation melanoma." (PMID 41492362, 2026). "The synergistic effect of trametinib and radiotherapy was also observed in NRAS/BRAF mutation melanoma cell line (D04, WM1631)." (PMID 41492362, 2026). "Compared with other studies of melanoma, we found fewer mutations in classical driver genes such as BRAF, NRAS or NF1." (PMID 41708869, 2026). "In the past decade, BRAF inhibitors combined with MEK inhibitors significantly improved the prognosis of BRAF mutation melanoma." (PMID 41492362, 2026). "We have identified a small molecule produced by a marine sponge as being able to inhibit PTCH1 efflux activity and increase the efficacy of vemurafenib treatment on BRAF-mutated melanoma cells in vitro and in vivo in mice." (PMID 42001685, 2026). "In melanoma cells with BRAF and NRAS mutations, HSPB8 plays an anti-tumor role by regulating processes such as autophagy." (PMID 41490177, 2026). "In the last two decades, targeted therapy has significantly improved the prognosis of melanoma with BRAF mutation, with vemurafenib and dabrafenib being approved by United States Food and Drug Administration (US FDA)." (PMID 41492362, 2026). "The BRAF V600E mutation is a validated therapeutic target in cancers such as melanoma, thyroid carcinoma, and colorectal cancer." (PMID 41497266, 2026). "Targeted therapies with BRAF-MEK inhibition also show adequate response rates in BRAF-mutated melanomas." (PMID 41580899, 2026).
melanoma (continued). "We conducted a systematic review of real-world data on adjuvant therapy in stage III melanoma to determine the best option for patients with BRAF V600 mutations." (PMID 39673834, 2025). "One of the earliest and most frequent genetic changes recognized in human melanoma is the BRAF mutation, occurring at a rate of 40.3%." (PMID 41198656, 2025). "Vemurafenib has redefined the therapeutic landscape for BRAF-mutant melanoma and exemplifies the clinical potential of mutation-targeted drug development." (PMID 41302945, 2025). "Over time, terms such as immunotherapy, metastasis, pathway, BRAF, BRAF mutation, colorectal cancer, and malignant melanoma have emerged as prominent research themes." (PMID 39897423, 2025). "BRAF V600E mutations were identified in 33 of 200 (17%) melanomas and 14 (7%) had other BRAF mutations (V600K/R)." (PMID 40869231, 2025). "Mutations in the monomeric GTPase gene RAC1 are the third most common hotspot mutation in melanoma after BRAF and NRAS mutations." (PMID 41109929, 2025). "If unsuitable for immunotherapy, patients with asymptomatic MBMs and BRAF V600-mutated melanoma can be offered BRAFi–MEKi [III, B; ESCAT I-A]." (PMID 39550033, 2025). "Another study focused on ERK1/2 inhibition in BRAF-mutated melanoma, as a way to interfere with the oncogenic Ras signaling." (PMID 40862737, 2025). "When excluding acral and facial melanomas, which have different dermoscopic patterns, the dermoscopic presence of ulceration was also statistically significantly associated with the presence of BRAF mutation in melanomas." (PMID 41010758, 2025). "The effectiveness of 1h was confirmed in the human MeOV and MeTA melanoma cell lines, bearing different BRAF mutations." (PMID 40650091, 2025). "The prognosis of patients diagnosed with advanced melanoma has dramatically improved since the introduction of anti-PD-1-based immunotherapy and targeted therapy with BRAF and MEK inhibitors for BRAF-mutated patients." (PMID 39796770, 2025). "In BRAF-mutated melanoma, CDK12 activity drives tumor proliferation and genomic stability, while the CDK12/13 inhibitor SR-4835 inhibits DDR gene expression, induces DNA damage, and impairs melanoma growth." (PMID 40075638, 2025). "Consistent with our results, GPX4 dependency of DTP cells induced by targeted TKI has also been found in HER2‐amplified breast cancer, EGFR‐mutated NSCLC, and BRAF‐mutated melanoma." (PMID 39369284, 2025). "Approximately 50% of malignant melanomas have mutations in BRAF, which promote melanin production through conformational activation of the MAPK (RAS/RAF/MEK/ERK) signaling pathway." (PMID 40932870, 2025). "In melanoma with BRAF/NRAS mutations, PRKN is downregulated, while BRAFV600E or MAPK inhibition can increase PRKN expression leading to cytostatic and apoptotic effects." (PMID 40862737, 2025). "The serine/threonine kinase BRAF is frequently mutated in several tumor types, including melanoma and non-small cell lung cancer (NSCLC)." (PMID 41282105, 2025). "In BRAF-mutated melanoma cells, the inhibition of ERK1/2 signaling leads to the induction of forkhead box D3 (FOXD3), which influences the sumoylation of SOX10." (PMID 40872623, 2025). "Mutations of the BRAF gene are the most frequent, detected in approximately 38.5% of melanomas, while NRAS mutations occur in about 16.4% and KIT mutations in around 10% of cases." (PMID 41007741, 2025). "Regarding targeted therapy, dabrafenib and trametinib also improved RFS and DMFS compared to placebo in BRAF-mutated stage III melanoma." (PMID 39796770, 2025). "Given the toxicity profile of anti-CTLA-4 and the duration of therapy investigated, adjuvant therapy with either anti-PD-1 agents or dabrafenib–trametinib for patients with BRAF-mutated melanoma is preferred." (PMID 39550033, 2025).